STAT3 (signal transducer and activator of transcription 3)
Diseases named in the same sentence as STAT3 in open-access papers (continued):
Sharing a sentence is not in itself a finding about the gene and the disease.
breast cancer (continued). "Notably, STAT3 can also be methylated on Lys49 and Lys180 by EZH2, the lysine methyltransferase subunit of the polycomb repressive complex 2 (PRC2) in glioblastoma, colon cancer, and breast cancer cell lines." (PMID 29728695, 2018). "Other investigators have demonstrated that a constitutively active mutant form of STAT3 expressed in immortalized human mammary epithelial cells induces expression of MMP9 mRNA and protein and furthermore that MMP9 expression correlates with nuclear pSTAT3 expression in breast cancer tissues." (PMID 29875329, 2018). "Furthermore, STAT3 can recruit the histone methyltransferase G9a to form a repressor complex that facilitates H3K9 dimethylation gene silencing marks at the promoter of miR-200c, in leptin-treated breast cancer cells." (PMID 29728695, 2018). "Indeed, mRNA analysis has also confirmed IL-6 receptor expression in IBC cells [73, Morrow unpublished observations], and IL-6/STAT3 signaling has been proposed to underpin the dynamic equilibrium between stem and nonstem breast cancer cells." (PMID 28607534, 2017). "Furthermore, STAT3 can act as a tumor suppressor or an oncogenic agent; for example, STAT3 suppresses brain tumor progression via PTEN and promotes progression in various breast cancer types." (PMID 28178652, 2017). "In a murine model of breast cancer, TAMs are also demonstrated to promote CSC phenotypes in breast cancer cells through the EGF-mediated STAT3/SOX-2 cascade, and this cross talk could be abrogated by small molecule inhibitors against EGFR or STAT3." (PMID 28337221, 2017). "Claudin-low tumors represent ~5-10% of all breast cancers, are often triple-negative and poorly differentiated, and have elevated activities of EGFR, proto-oncogene tyrosine kinase Src, transforming growth factor β (TGFβ), and signal transducer and activator of transcription 3 (STAT3) pathways." (PMID 28148288, 2017). "Thus, we conclude that TNF-α promotes the growth of breast cancer through the positive feedback loop of TNFR1/NF-κB (and/or p38)/p-STAT3/HBXIP/TNFR1.Our finding provides new insights into the mechanism by which TNF-α drives oncoprotein HBXIP in the development of breast cancer." (PMID 28938560, 2017). "However, we did not see any effect on STAT3 activation when the same mutation was introduced into FRK kinase domain and transfected in breast cancer cells." (PMID 29348886, 2017). "Given that system xc- is intricately involved in redox homeostasis, we previously examined whether representative STAT family members regulate xCT expression, demonstrating by ChIP analysis that STAT3 and STAT5A are able to directly bind to the xCT promoter in MDA-MB-231 human breast cancer cells." (PMID 27513743, 2016). "Thus, prevention or inhibition of deregulation in the PI3K/STAT3/PTEN signaling pathway could be beneficial for the treatment and better outcome of breast cancer." (PMID 26762586, 2016). "In this study, we demonstrate that different breast cancer cell lines after treatment with clinically relevant concentrations of 5-fluorouracil, doxorubicin, or paclitaxel enrich CSCs, increase expression of IL-6, IL-8, and MCP-1 cytokines, and up-regulate activation of NF-κB and Stat3 pathways." (PMID 26506421, 2016). "The interaction between hyaluronan and CD44 activates the stem cell marker Nanog, Stat-3-mediated MDR1 gene expression, and ankyrin-regulated multidrug efflux in breast and ovarian tumor cells, and it can also lead to Bcl-2 expression and chemoresistance in breast cancer cells." (PMID 25605243, 2015). "Importantly, CH12 in combination with trastuzumab had a synergistic inhibitory effect on EGFRvIII+HER2+ breast cancers in vitro and in vivo via attenuating the phosphorylation of EGFR and HER2 and their downstream signal pathways more effectively and reversing STAT3 feedback activation." (PMID 26474285, 2015).
breast cancer (continued). "Moreover, the IL-6/STAT3/JAK2 pathway is involved in the maintenance of stem cell–like cancer cells because CD44+CD24+ and CD44+CD24− breast cancer cells have high phospho-STAT3 via their expression of genes such as IL6, PTGIS, and HAS1, which activate an autocrine loop." (PMID 26515594, 2015). "Moreover, the combination of trastuzumab and CH12 could synergistically inhibit the growth of EGFRvIII+HER2+ breast cancer via attenuating phosphorylation ERK and AKT more effectively and reversing STAT3 feedback activation." (PMID 26474285, 2015). "Immunoblotting studies revealed that levels of Stat3β protein, but not Stat3α, in breast cancer cell lines positively correlated with overall pStat3 levels, suggesting that Stat3β may contribute to constitutive Stat3 activation in this tumor system." (PMID 25268166, 2014). "Furthermore, in primary breast cancers, no increase was seen in miR-146b with increasing STAT3 tyrosine phosphorylation." (PMID 24762632, 2014). "Additionally, STAT3 has been detected mostly in breast cancer cells, but not in normal breast tissues." (PMID 24694753, 2014). "Despite the fact that a sizable body of evidences highlight that STAT3 is inappropriately activated in a vast percentage of breast tumors, its biological significance is controversial and its concrete role in breast cancer initiation and/or progression is not fully established." (PMID 25026286, 2014). "Here, we showed that sorafenib did not efficiently increase SHP-1 activity and did not effectively inhibit p-STAT3 in several breast cancer cell lines such as MDA-MB-231 and MDA-MB-468 cells or in MDA-MB-468 xenograft tumors, as compared with sorafenib analogues SC-1 and SC-43." (PMID 23938089, 2013). "In breast cancer cells from representative breast tumor tissue from a breast cancer patient, p-STAT3 showed prominent nuclear expression and negative cytoplasmic expression (upper left), but negative nuclear and cytoplasmic expression compared to adjacent normal breast cells (lower left)." (PMID 23938089, 2013). "However, the role of STAT3 signaling in ALDH+ and ALDH+/CD44+/CD24− subpopulations of breast cancer cells is unknown." (PMID 24376586, 2013). "Furthermore, LLL12 inhibited STAT3 phosphorylation and tumor cell proliferation, induced apoptosis, and suppressed tumor growth in xenograft and mammary fat pad mouse models from ALDH+ breast cancer cells." (PMID 24376586, 2013). "In corroborating work, targeting the SH2 domain of Stat3 with a novel small molecule decreased the percentage of cells expressing TIC markers (CD44+/CD24−/low and ALDH+) and mammosphere formation in p-Stat3 overexpressing human breast cancer xenografts in SCID-beige mice." (PMID 22879872, 2012). "In addition, HSE regulates the STAT3, VEGF and VEGF-R2 signal pathways in human breast cancer cells and thus may be an anti-angiogenic agent." (PMID 22792362, 2012). "Therefore, the Stat3 transcription factor is in part responsible for promoting Jab1 transcription in breast cancer cells and is either not present or not as active in the MCF-10A and MCF-10F cells." (PMID 21689417, 2011). "Moreover, it has been shown that STAT3 inhibition by restoration of its inhibitor, suppressor of cytokine signalling (SOCS-1), results in induction of Caveolin-1, a tumour suppressor gene in breast cancer." (PMID 22567347, 2011). "Using a model system of paired breast cancer cell lines, they found that co-activation of STAT5 and STAT3 leads to decreased proliferation and increased sensitivity to the chemotherapeutic drugs paclitaxel and vinorelbine compared with cells that have only STAT3 activation." (PMID 20433750, 2010). "However, no linkage has yet been made between LIF expression and Stat3 activation in mammary tumors." (PMID 17925034, 2007).
breast cancer (continued). "However, the elevated phosphorylation on mTOR and Stat3 was noticeably differed from that on PDK-1 in various stages of breast cancer, indicating these molecules are not in a single linear signalling cascade regulated by PDK-1." (PMID 16288304, 2005). "However, whether RSL3 modulates STAT3 to regulate autophagy and apoptosis in PARPi-resistant breast cancer has not been explored." (PMID 41463402, 2025). "Moreover, a formulation containing sulforaphane and cyclodextrin reduced breast cancer stem cell viability in primary and metastatic ER+ samples from patients, through decreased ALDH positive population, the prevention of tamoxifen enrichment and the inhibition of metastasis and STAT3 activity." (PMID 39859345, 2025). "In vitro studies have shown that IL-1 activation in 4T1 cells involves the intracellular signals STAT3, JNK, ERK, AKT, and NF-κB, which may be involved in cell proliferation and survival, but phosphorylation occurs only at the JNK, ERK, and AKT levels in Hs578T human breast cancer cells." (PMID 38956273, 2024). "Although this previous study did not determine whether IL-22 activated STAT3 in breast cancer cells to reduce their sensitivity to NK cell-meditated cytotoxicity, solid evidences confirm that tumor cell-intrinsic STAT3 activation can impair NK cell antitumor immunity via intricate mechanisms." (PMID 38596684, 2024). "Furthermore, evidence suggests that ROS contributes to 27HC-induced breast cancer cell invasion and angiogenesis by regulating reversion-inducing-cysteine-rich protein with Kazal motifs (RECK)/STAT-3 signaling via DNA methylation 157 and STAT-3/VEGF signaling 158, respectively." (PMID 38617549, 2024). "Our findings firstly illustrated that circPAPD4/miR-1269a/CREBZF/STAT3/ADAR1 positive feedback loop mediated BC progression, and delivering CREBZF mRNA nanoparticles suppressed BC progression in vitro and in vivo, which might provide novel insights into therapeutic strategies for breast cancer." (PMID 37264406, 2023). "However, in patients with estrogen receptor-negative (ER(−)) breast cancer and triple-negative breast cancer (TNBC), multivariate analysis showed that higher p-STAT3 expression was significantly associated with a short relapse-free survival (p = 0.029, HR 5.37, 95%CI 1.19–24.29)." (PMID 35314590, 2022). "Furthermore, OSM and OSMR are upregulated in response to STAT3 activation and the signaling triggered by this cytokine promoted the expression of metalloproteinases MMP3, MMP12, and MMP14, that are relevant for remodeling normal mammary tissue, but would also facilitate mammary tumor invasiveness." (PMID 35163731, 2022). "The importance of active STAT3 in TNBC has been recently unveiled by Nakagawa and colleagues, who reported that the nuclear expression of pSTAT3 was significantly associated with short relapse-free survival and a poor prognosis in TNBC patients, but not in ER(+) breast cancer women." (PMID 35955836, 2022). "However, it is not clear how STAT3 correlates with EZH2 in breast cancer." (PMID 34335938, 2021). "Moreover, the study has uncovered a previously unrecognized positive-feedback loop in the STAT3–TINCR–EGFR signaling axis in tumorigenesis, and this feedback loop could thus represent a new target in pharmacological strategies for treating human breast cancer." (PMID 33446634, 2021). "In the current study, we did not observe similar involvement of STAT3 in oral cancer, suggesting that cell type differences between oral cancer (squamous cell carcinoma) and breast cancer (adenocarcinoma) may contribute to differences in the MRE11-preferential signaling pathways." (PMID 33927349, 2021). "Importantly, STAT3 knockdown did not affect cell proliferation, cell cycle distribution or basal migration activity, but notably it prevented increased migration of breast cancer cells in response to opioid exposure." (PMID 33465556, 2021).
breast cancer (continued). "Previous studies demonstrate that STAT3 activation not merely act as a predictive biomarker for downregulated immune cells response, but also the type of immunomodulator that is strongly associated with programmed death ligand 1 (PD-L1) expression in the TME of breast cancer." (PMID 33957948, 2021). "Similarly, targeting of the STAT3 upstream, downregulating the intercellular pSTAT3-Y705 activity and upregulating glycolysis by leptin or PD-1 intervention markedly ameliorated the CD8+ T effector cells function in TME and prevented the development of breast cancer." (PMID 33957948, 2021). "Indeed, in breast cancer cell lines MDA-MD-231 and MDA-MD-468 (TNBC cells), NS8593 suppresses TRPM7 Mg2+-dependent currents, increasing the apoptotic and antiproliferative effects induced by TRAIL via a decrease in c-FLIP as well as suppressing the phosphorylation of STAT3, respectively." (PMID 34944940, 2021). "Importantly, SIRT4 inhibits the phosphorylation and nuclear translocation of STAT3, thereby inhibiting the STAT3 signaling pathway, and amplification of the target genes MYC and CCND1 of the STAT3 signaling pathway provide tamoxifen resistance in ER-positive breast-cancer cells." (PMID 33585187, 2020). "Additionally, through regulation of EMT/stemness, STAT3 may also play a role in regulating drug resistance, as it was shown that in human breast cancer, feedback activation of the IL6-STAT3 loop induced EMT and cancer stem cell features, leading to resistance to PI3K inhibitors." (PMID 32391382, 2020). "However, all of these promoting effects could be attenuated or abolished by treatments with the G-CSF-neutralizing antibody or a Stat3-targeting small-molecule inhibitor, demonstrating that G-CSF is a crucial and functional mediator in the adipocyte/CAA–breast cancer crosstalk." (PMID 32242230, 2020). "In addition, when STAT3 is not concurrently activated with STAT5 (which make up 7% of breast cancer tissues), STAT5 may also act as an oncogene." (PMID 32872372, 2020). "In addition, miR-19a-3p has been shown to inhibit breast cancer progression and metastasis by inducing a macrophage phenotype switch from M2 to M1 by targeting Fos-related antigen 1 (Fra-1), vascular endothelial growth factor (VEGF), and signal transducer and activator of transcription 3 (STAT3)." (PMID 31766495, 2019). "This work identifies Stat3 as a potential therapeutic target that may radiosensitise cells prior to conventional radiation therapy and provides a basis for the clinical application of radiation combined with MSC therapy, thus suggesting a more effective treatment for breast cancer patients." (PMID 30297887, 2018). "Indeed, STAT3 is supposed to be a promising therapeutic target of novel anticancer drugs like methyl ester derivative of synthetic triterpenoid which have been tested in a relevant model of ER negative breast cancers." (PMID 28301550, 2017). "Additionally, prolonged activation of STAT3 leads to low expression of let-7 and miR-200 coupled with the upregulation of ZEB1 in OSM-triggered EMT, which contributes to the acquisition of the mesenchymal phenotype and invasive capability as well as promotion of breast cancer progression." (PMID 26631279, 2015). "To determine if an association between GRN and STAT3 could be found in breast cancer cells that do not have constitutively active PY-STAT3, we examined SKBR-3 cells, a HER2-overexpressing breast cancer cell line in which STAT3 can be specifically activated by cytokine stimulation." (PMID 26000098, 2015). "In vitro assays showed that the mechanism of IL-19 in 4T1 cells is activating the intracellular signals STAT3, JNK, ERK, AKT, and NF-κb, which may be involved in cell proliferation and survival, but phosphorylation occurred only on JNK, ERK, and AKT in Hs578T human breast cancer cells." (PMID 23710200, 2013).
breast cancer (continued). "Pan-cancer analysis revealed a negative correlation between the expression of STAT3, VEGFA, ESR2, and ABCG2 and breast cancer patient survival." (PMID 41121538, 2025). "In our study, we first reported that APX2009 reduces STAT3 transcriptional activity without affecting its protein levels, suggesting that the redox domain of APE1 also regulates STAT3 in breast cancer." (PMID 41090323, 2025). "ELK1, but not SRF or STAT3, was reported to regulate both the basal and epidermal growth factor induced MCL1 transcription in breast cancer cells." (PMID 40075071, 2025). "This study evaluates the antitumor activity of BO for the first time and confirms that BO extracted from A. vaginata exhibits therapeutic potential against various types of breast cancer, including TNBC, by modulating STAT3, a non-surface receptor target." (PMID 40076902, 2025). "Our findings uncover the regulatory mechanism by which OVOL2 represses FAO in breast cancer and propose that targeting JAK/STAT3‐FAO is a potential strategy for OVOL2‐absent TNBC therapy." (PMID 38627980, 2024). "Breast cancer MDA-MB-231 and MDA-MB-468 lines were treated with H182 for 2 h at concentrations of 0–3 μM that inhibit constitutive and ligand-induced Stat3 activation, stimulated or not with EGF for 12 min, and whole-cell lysates were prepared." (PMID 35276290, 2022). "In lung and breast cancer cells, leptin treatment has amplified the levels of soluble ICAM-1 by upregulating ERK, GSK3αβ, JAK1/2, STAT3 and focal adhesion kinase (FAK) signaling without affecting the expression of cell surface ICAM-1." (PMID 34588926, 2021). "However, the single silencing of Notch1 could be not sufficient to regain breast cancer cell sensitivity to doxorubicin; therefore, targeting multiple pathways including STAT3 and β-catenin together with Notch1 could provide a more synergistic action with doxorubicin." (PMID 34680255, 2021). "On the other hand, lots of TFs, like EN1, STAT3, SOX9, and FOXM1, showed essential oncogenic functions in non-luminal breast cancer." (PMID 34249704, 2021). "In a follow-up study, these compounds also significantly reduced the phosphorylation of STAT3, a direct BRK target, and were found to modestly induce cell death of non-adherent breast cancer cells." (PMID 33391524, 2021). "But LIF does not seem to be solely dependent on STAT3 activation in order to be pro-oncogenic, and some have even pointed to tumor cell dormancy induction via a LIF : LIFR : STAT3 axis in breast cancer to bone marrow metastasis." (PMID 34395259, 2021). "Although ODZ10117 inhibited the tyrosine phosphorylation of STAT3, it did not significantly affect other STAT family proteins, including STAT1, STAT5, and STAT6, in breast cancer cells and Hodgkin’s lymphoma cells." (PMID 31684051, 2019). "Western blotting showed that, compared with the negative control cells, STAT3 expression was weaker in the nucleus and stronger in the cytoplasm following SIRT4 overexpression in both breast cancer cell lines." (PMID 31573734, 2019). "We also report that the levels of STAT-3 and JAK-2 were found to be constitutively active in the BT549 breast cancer cell line and treatment with HGF and/or BFE had no bearing on the phosphorylational status." (PMID 30314527, 2018). "In contrast, a comparison between the MCF-7 cell line with another ERα-positive breast cancer cell line, T47D, revealed almost no similarities in the responses to CAF-CM other than an increase in STAT3 phosphorylation." (PMID 29774124, 2018). "STAT1, but not STAT3, increased basal (MT/Shc313F/313F) and IFNγ-inducible (MT/ShcA+/+; MT/Shc2F/2F) surface MHC class I expression on breast cancer cells." (PMID 28276425, 2017). "Similar to the effects of HER2 and STAT3 inhibition, survivin depletion increased radiation-induced cell death and reduced clonogenic survival of HER2-positive SKBR3 breast cancer cells, but it did not affect HER2 and STAT3 phosphorylation." (PMID 26755645, 2016).